TLR4 (toll like receptor 4)
Diseases named in the same sentence as TLR4 in open-access papers (continued):
Sharing a sentence is not in itself a finding about the gene and the disease.
periodontitis (continued). "In vitro cell proliferation assay was performed to investigate the effects of PTCSC3 and TLR4 on proliferation of periodontitis-affected PDLSCs." (PMID 31196168, 2019). "Linear regression showed that expression levels of PTCSC3 and TLR4 were significantly and inversely correlated in periodontitis-affect PDLSCs." (PMID 31196168, 2019). "While the immunohistochemical or immunofluorescence studies have shown elevated TLR-2 and TLR-4 protein expression in the gingival epithelial cells in periodontitis, molecular analyses of TLR-2 and TLR-4 transcripts have yielded variable results." (PMID 30571680, 2018). "Previously, we observed that the relative expression of TLR-4 mRNA in SEC from periodontitis saliva is higher than that in SEC from healthy saliva." (PMID 30571680, 2018). "Recently, levels of microbial ligands for TLR-2 and TLR-4 have been reported to be higher in the saliva of periodontitis patients." (PMID 30571680, 2018). "The aim of this study was to evaluate the effects of IL-36γ on periodontitis byenhancing the TLR4 and MAPK signaling pathways." (PMID 30443300, 2018). "IgG in sera from periodontitis subjects containing elevated aCL stimulated TLR4 activation to a much greater extent than did samples from periodontally healthy individuals." (PMID 30192824, 2018). "Altered expression profiles of CD14, TLR-2 and TLR-4 have been previously reported in periodontitis." (PMID 30571680, 2018). "We focused on TLR2 and TLR4 activation and noted that IgG from aCL-containing periodontitis sera activate TLR4 in tissue culture." (PMID 30192824, 2018). "On the other hand, while the sTLR-2 and the paired epithelial cell associated TLR-2 mRNA exhibited a direct correlation (r2 = 0.62), that of sTLR4 and TLR-4 mRNA exhibited an inverse correlation (r2 = 0.53) in the periodontitis cohort." (PMID 30571680, 2018). "We also determined TLR4 activation by IgG from 5 periodontitis patients with normal levels of aCL, and observed that these samples failed to stimulate TLR4 to a greater extent than IgG samples from periodontally healthy controls." (PMID 30192824, 2018). "Next, we examined the ability of IgG from periodontitis subjects’ sera containing elevated levels of aCL to activate a first trimester human trophoblastic cell line (HTR8/SV.neo) via TLR4." (PMID 30192824, 2018). "LPS, a bacterial component, is a known pathogen of periodontitis and has also been identified as a ligand for TLR4." (PMID 29361674, 2018). "Evidence suggests that both TLR2- and TLR4-positive cells are upregulated in the gingival tissues in periodontitis." (PMID 28326084, 2017). "In the present study, we investigated the effects of GM-0111 on molecular events associated with periodontitis, ranging from the anti-inflammatory effects mediated by TLR2 and TLR4, RANKL-induced osteoclast formation, and pathogenic bacterial growth." (PMID 27308827, 2016). "As chronic periodontitis models, rGGT was administered to the gingival sulcus of the upper jaws of WT and Tlr4−/− mice." (PMID 27775020, 2016). "We showed that periodontitis impairs hepatic insulin signaling via TLR4 and that this impairment was less in mice with whole body TLR4 loss of function (LOF) when mice were fed a HF diet." (PMID 26317345, 2015). "For example, by using immunohistochemistry, one study showed that periodontitis decreased TLR4 but another study demonstrated that periodontitis increased TLR4 level in the gingival epithelium." (PMID 26581717, 2015). "This study investigated the effects of T2DM and periodontitis on TLR4, CD14, MD-2 and MyD88 mRNA expression in surgically removed periodontal tissues." (PMID 26581717, 2015). "We conclude that LPS from periodontitis sites has a pivotal role in triggering the development of GI/IR through a mechanism that involves TLR4 expression by resident macrophages/Kupffer cells in the liver." (PMID 26317345, 2015). "The TLR4/MyD88 pathway is a well-established regulatory axis in periodontitis." (PMID 41459503, 2025).
periodontitis (continued). "TLR4 rs2149356 polymorphism may modulate inflammatory response in ESRD and periodontitis patients, although findings remain exploratory." (PMID 41002387, 2025). "The significant role of TLRs in periodontitis was underscored through a systematic literature review and subsequent meta-analysis, which assessed the association between plasma and salivary levels of TLR2 and TLR4 in individuals with CP versus SPHS." (PMID 40371381, 2025). "This systematic review and meta-analysis aimed to systematically analyze and quantify the differences between TLR2 and TLR4 levels in the saliva and plasma of individuals with chronic periodontitis (CP) and systemically and periodontally healthy subjects (SPHS)." (PMID 40371381, 2025). "Associations of polymorphisms A-2570G, A896G, and C1196T of the TLR4 gene in individuals with and without periodontitis." (PMID 40552316, 2025). "Accordingly, periodontitis may contribute to tumor progression and development by stimulating TLR4, which in turn leads to a poorer OS and DSS." (PMID 38376617, 2024). "Five key genes associated with ICD (ENTPD1, TLR4, LY96, PRF1 and P2RX7) may be diagnostic biomarkers of periodontitis and future therapeutic targets." (PMID 39555084, 2024). "PTCSC3 and TLR4 were dysregulated in individuals affected by periodontitis." (PMID 39063437, 2024). "Therefore, TLR4 in immune activation wound provide innovative thinking for the treatment of periodontitis." (PMID 36761293, 2023). "NAC‐S2 ameliorate inflammation mediated by TLR4/NF‐κB pathway in mouse periodontitis models." (PMID 37647428, 2023). "All of these indicated the effect of NAC‐S2 on periodontitis was TLR4/Myd88 dependent." (PMID 37647428, 2023). "The role of NAC‐S2 on periodontitis is TLR4/Myd88 dependent." (PMID 37647428, 2023). "First, the effect of NAC‐S2 on periodontitis is achieved in a TLR4/Myd88‐dependent manner." (PMID 37647428, 2023). "In addition, we for the first time proposed the circ_0099630/miR-409-3p/TLR4 network to illustrate the new mechanism of circ_0099630 in periodontitis." (PMID 38007427, 2023). "Furthermore, the expression of Toll-like receptor 4 (TLR4) on mast cells has been demonstrated to be positively correlated with the severity of chronic periodontitis." (PMID 39916927, 2023). "Besides, we found that TLR4 mRNA expression was positively correlated with circ_0099630 expression in periodontal tissues of periodontitis." (PMID 38007427, 2023). "Circ_0099630 knockdown relieved LPS-induced HPDLC injury by miR-409-3p/TLR4 axis, suggesting that circ_0099630 might be a potential target for periodontitis treatment." (PMID 38007427, 2023). "Collectively, LPS could promote the macrophages into M1 status via TLR2/TLR4/NF-κB p65 signaling pathway partly by sEV-mediated microRNA-433-3p, which could be a potential therapeutic target for periodontitis." (PMID 37351818, 2023). "One of the primary virulence factors of periodontitis, Pg-LPS, targets TLR4, which activates the NF-kB signaling pathway and triggers the secretion of inflammatory cytokines such as TNFα, IL-6, and chemokines, recruiting monocytes/macrophages to the site of infection." (PMID 38249288, 2023). "For example, the TLR2 pathway has been confirmed both in the pathogenesis of periodontitis and peri-implantitis; LPS and TLR4 pathway has been widely studied for the regulation in periodontitis and peri-implantitis; and also other PRRs pathways should be considered." (PMID 36685503, 2022). "Since gram-negative bacteria, such as P. gingivalis, are major contributors to microbial dysbiosis and inflammation in periodontitis, inhibiting the LPS-induced activation of TLR4 may be a potential mechanism to reduce inflammation in periodontitis." (PMID 35628390, 2022).
periodontitis (continued). "For example, lipopolysaccharide, an outer membrane component of Gram-negative bacteria including Porphyromonas gingivalis (one of the pathogens of periodontitis), can be recognized by toll like receptor 4 (TLR-4) on the surface of monocytes/macrophages or DC, resulting in innate immune response." (PMID 35371044, 2022). "A multi-centre study on 617 periodontitis patients with arthritis reported lack of association between the TLR4 SNP (Asp299Gly) and the presence of P. gingivalis." (PMID 35122548, 2022). "Moreover, the correlation analysis showed that the TLR4 expression was significantly and negatively correlated with miR-511-3p expression in periodontitis." (PMID 33679417, 2021). "Our data revealed that circMAP3K11 prohibits the functions of PDLSCs via sponging miR-511-3p to enhance TLR4 expression in periodontitis environment, which provides novel insights and scientific information for clinical enhancement of periodontal tissue regeneration." (PMID 33679417, 2021). "In Tlr2 KO and Tlr4 KO mice, the bone loss caused by ligation-induced periodontitis did not decrease." (PMID 34445604, 2021). "TLR4 has been proved to be crucial in periodontitis pathogenesis." (PMID 33679417, 2021). "Therefore, we conclude that circMAP3K11/miR-511-3p/TLR4 regulatory axis affects the functions of PDLSCs and increases the inflammatory responses in the development of periodontitis." (PMID 33679417, 2021). "Meanwhile, both in vitro and in vivo studies indicated that circMAP3K11 could reverse the effects of miR-511-3p in periodontitis, which further confirmed that circMAP3K11 functioned as a ‘sponge’ of miR-511-3p to positively regulate the expression of TLR4." (PMID 33679417, 2021). "LPS, as a ligand for TLR4, is an outer membrane component of Gram-negative bacteria and known to be a major definitive pathogenic factor of inflammatory bone resorption in periodontitis." (PMID 34172796, 2021). "SNPs in CD14, NF-κΒ, TLR2, and TLR4 are no risk modulators for preexisting CV events or severe periodontitis in CV patients." (PMID 34305452, 2021). "A large body of evidence has proven the involvement of TLR4 in periodontitis." (PMID 33679417, 2021). "In the current study, the dual-luciferase reporter assay confirmed that TLR4 is a direct target gene of miR-511-3p and correlation analysis, RT-PCR and western blot assays signposted that the expression of miR-511-3p is negatively correlated with TLR4 expression in periodontitis." (PMID 33679417, 2021). "Gram-negative bacteria are the major pathogen involved in periodontitis, and their main pathogenic component is the lipopolysaccharide (LPS) that is primarily recognized by TLR4." (PMID 33679417, 2021). "The expression of miR-511 in periodontitis gingiva was reported to be significantly higher than that in healthy gingiva (more than four fold) and plays crucial roles in regulating TLR4 expression in several inflammatory diseases." (PMID 33679417, 2021). "Therefore, inhibition of TLR4-mediated NF-κB signaling is considered as an effective therapeutic approach for treating periodontitis." (PMID 32735017, 2020). "This indicated that periodontitis induced neuroinflammation through TLR4/NF-κB pathway cascades." (PMID 32714134, 2020). "There are several reports on the importance of TLR4 in periodontitis." (PMID 33322059, 2020). "TLR2 and TLR4 are the predominant TLRs activated in periodontitis." (PMID 32793243, 2020). "Mechanically, knockdown of TRIM52 could mitigate LPS-induced inflammatory injury in periodontitis through TLR4/NF-κB signaling." (PMID 32735017, 2020). "Our findings indicated that periodontitis induced by topical application of P. gingivalis-LPS could contribute to learning and memory impairment via neuroinflammation induced by TLR4/NF-κB signaling pathway activation in SD rats." (PMID 32714134, 2020).
periodontitis (continued). "Therefore, the overall goal of the present study was to investigate the effects of chronic exposure to TLR2 and TLR4 agonists on the inflammatory adaptive immune response, mimicking an inflammatory environment such as apparent in chronic periodontitis." (PMID 31817424, 2019). "However, the TLR4, OPG, and RANKL polymorphisms were involved in the pathogenesis of periodontitis when considering gender and smoking habits." (PMID 31281226, 2019). "Under chronic inflammatory conditions such as periodontitis in contrast to the TLR2 upregulation expression of TLR4 decreased, which may prevent from inflammatory exacerbation, i.e., tissue and bone destruction through containment of the inflammatory response." (PMID 30837987, 2019). "Furthermore, the overall aim of the present study was to investigate the effects of chronic exposure to TLR2 and TLR4 agonists on the inflammatory adaptive immune response, mimicking an inflammatory environment such as apparent in chronic periodontitis." (PMID 31817424, 2019). "Thus, the aim of this study was to evaluate the influence of the polymorphisms in TLR4 (rs4986790 and rs4986791), CD14 (rs2569190), RANKL (TNFSF11, rs2277438), and OPG (TNFSF11B, rs3102735) in the development of periodontitis." (PMID 31281226, 2019). "Thus, the aim of this study was to evaluate the influence of the TLR4 A896G (rs4986790), TLR4 C1196T (rs4986791), CD14 C-260T (rs2569190), RANKL (TNFSF11, rs2277438), and OPG (TNFSF11B C163T, rs3102735) polymorphisms in periodontitis." (PMID 31281226, 2019). "The TLR4 896 A/G genotype was a risk factor for periodontitis in males (OR = 2.86), and the TLR4 1196C/C genotype was a risk factor for nonsmoking males (OR = 1.85) when compared to women." (PMID 31281226, 2019). "The key finding of the present study is that PTCSC3 was downregulated in periodontitis-affected PDLSCs and overexpression of PTCSC3 may improve periodontitis by inhibiting the proliferation of PDLSCs and downregulating the expression of TLR4." (PMID 31196168, 2019). "Interestingly, our study proved that PTCSC3 was likely an upstream inhibitor of TLR4 in periodontitis-affected PDLSCs." (PMID 31196168, 2019). "In multivariate analyzes, nonsmoking men carrying the TLR4 896 A/G and 1196 C/C genotypes showed approximately 200% risk of periodontitis development compared to women carrying the wild genotypes." (PMID 31281226, 2019). "Thus, it appears that aCL from periodontitis patients can be proinflammatory, activating cells via TLR4." (PMID 30192824, 2018). "We hypothesized that IgG aCL from periodontitis patients could activate TLR4, thus explaining its ability to stimulate inflammatory cytokine release from trophoblasts and endothelial cells." (PMID 30192824, 2018). "PAMPs of TLR2 and TLR4 have been shown to be elevated in saliva of periodontitis patients." (PMID 30571680, 2018). "Interestingly, altered expression of TLR-4 has been described in periodontitis which suggests a role for this receptor in pathogenesis of AP." (PMID 28210435, 2017). "TLR-4 polymorphisms of Asp299Gly and Thr399Ile have not been associated with aggressive periodontitis (AgP) or chronic periodontitis in previous reports." (PMID 28210435, 2017). "The Tlr4-deficiency worsened the periodontitis in the C57BL/10J mouse, but not in the BALB/cJ mouse." (PMID 29163477, 2017). "The TLR4 was reported to be unmethylated in both healthy subjects and periodontitis patients." (PMID 29201597, 2017). "In the present study, we investigated whether GM-0111 disrupts events associated with periodontitis such as the growth and biofilm formation of P. gingivalis, TLR2/TLR4-mediated cellular activation and osteoclast formation in vitro." (PMID 27308827, 2016). "Thus, it was not clear from these results if impaired insulin signaling was due to less severe periodontitis or due to an inability of TLR4 (LOF) animals to respond to periodontitis/LPS, particularly in the liver." (PMID 26317345, 2015).
periodontitis (continued). "However, in this model system, the severity of periodontitis was much less in TLR4 LOF animals compared to TLR4 WT animals." (PMID 26317345, 2015). "This further suggests that TLR4 activation of Kupffer cells in the liver may play a major role in determining the effect of periodontitis on glucose tolerance." (PMID 26317345, 2015). "We therefore tested the hypothesis that periodontitis induces the development of GI/IR through a liver Toll-like receptor 4 (TLR4) dependent mechanism." (PMID 26317345, 2015). "In this study, we hypothesized that the expression of TLR4 or TLR4-associated molecules such as CD14, MD-2 and MyD88 are regulated by periodontitis and T2DM." (PMID 26581717, 2015). "This may result in lower cytokine production in the periodontitis sites resulting in decreased levels of cytokines in the systemic circulation compared with TLR4 WT mice." (PMID 26317345, 2015). "Thus, in order to differentiate between the two proposed mechanisms, we developed a model in which the phenotype of TLR4 differs between the two sites in the presence of chronic periodontitis." (PMID 26317345, 2015). "Our findings suggest that TLR4 or the NF-κB pathway might serve as a new therapeutic target for periodontitis." (PMID 24887697, 2014). "In addition, TLR2 and TLR4 mRNAs are significantly downregulated in the gingival tissue of patients with chronic periodontitis as compared to healthy persons, suggesting that the oral mucosa develops endotoxin tolerance in chronic periodontitis." (PMID 18799018, 2008). "CBD significantly reduced bone loss in the experimental periodontitis model, downregulated TNF-α, and reduced TLR4 expression in gingival tissues, suggesting that CBD, particularly in topical form, could be an effective therapeutic agent for treating periodontitis." (PMID 40332414, 2025). "It was reported that TLR4 activated the NF-κB signaling pathway to induce the release of pro-inflammatory factors, and Resveratrol played protective effects against experimental periodontitis in mice via inhibiting the phosphorylation of NF-κB signaling molecules, including p65, p38MAPK, and STAT3." (PMID 38007427, 2023). "Likewise, the expression of TLR4 mRNA was also significantly increased in periodontitis patients." (PMID 38007427, 2023). "In a study evaluating periodontitis, Cyanobacteria was demonstrated to modulate a pro-inflammatory response in the oral mucosa through a complex interaction of lipopolysaccharide (LPS)-mediated Toll-Like Receptor 4 (TLR4) blockade, IL-6 production, and miRNA expression." (PMID 36360258, 2022). "However, it should be emphasized that meta-analyses have not confirmed the association of this SNP in the TLR4 gene with periodontitis, even after stratification for ethnicity and disease severity." (PMID 34305452, 2021). "Upon binding of lipopolysaccharide, the Toll-like receptor-4 activates the inflammatory cascade system ultimately leading to the synthesis and release of pro-inflammatory cytokines and proteinases which are potential stimulators for tissue destructive effects in periodontitis." (PMID 34481488, 2021). "Therefore, TLR4 may play an important role in the progression of periodontitis, in which stimulation by Mfa1 may play a role." (PMID 33322059, 2020). "Therefore, the meta-analysis on the relationship between TLR-2 gene polymorphism and periodontitis susceptibility has not been reported alone, while the meta-analysis on TLR-4 and CD14 has been published; the conclusions are still inconsistent." (PMID 32831974, 2020). "Therefore, lncRNA PTCSC3 may regulate the proliferation of PDLSCs and TLR4 expression to improve periodontitis." (PMID 31196168, 2019). "Furthermore, the activation of TLR2 and TLR4 are found to be related with gingivitis and periodontitis in vivo, in line with our study where we found that the gingivitis biofilm induced more upregulation of TLR4 transcription compared to commensal and cariogenic biofilms." (PMID 31448244, 2019).